CYP1B1 (cytochrome P450 family 1 subfamily B member 1)
Diseases named in the same sentence as CYP1B1 in open-access papers (continued):
Sharing a sentence is not in itself a finding about the gene and the disease.
bladder cancer (9 papers, 2007 to 2025). "In bladder cancer, CYP1B1 is associated with lymph node metastasis, and its expression increases with the progression of this disease." (PMID 40989158, 2025). "CYP1B1 upregulates in the advanced stages of bladder cancer and participates in the activation of procarcinogen." (PMID 39351147, 2024). "By using immunohistochemistry, expression of CYP4Z1 and CYP1B1 was evaluated in a panel of different types of bladder cancer, and the enzymes’ relation to histopathological features were assessed." (PMID 33692504, 2021). "CYP4Z1 and CYP1B1 proteins are expressed at much higher rate in bladder cancer than in corresponding normal tissues." (PMID 33692504, 2021). "The expression profiles of CYP4Z1 and CYP1B1 suggest that both enzymes have the potential to be biomarkers or targets for novel anticancer therapy for bladder cancer." (PMID 33692504, 2021). "The current study investigated the CYP4Z1 and CYP1B1 expressions across a panel of different types of bladder cancer to confirm the hypothesis that CYP4Z1and CYP1B1 expressions may present novel opportunities for the development of new treatments for bladder cancer." (PMID 33692504, 2021). "Results showed an increased expression of CYP4Z1 (54.3%) and CYP1B1 (76.9%) in the majority of bladder cancers compared to weak or lack of expression of both enzymes in normal tissues." (PMID 33692504, 2021). "The basal PORlo bladder cancer cell lines T24 and SCaBER were used as in vitro models of POR suppression in MIBC and showed no/low inducible CYP1 enzyme activity, respectively despite CYP1A1 and CYP1B1 transcripts being ITE‐inducible." (PMID 29323757, 2018). "However, our study is the first to report high CYP1B1 expression in a large panel of bladder cancers, as opposed to corresponding normal tissues." (PMID 33692504, 2021).
endothelial dysfunction (9 papers, 2018 to 2025). In vascular diseases, endothelial dysfunction is a systemic pathological state of the endothelium (the inner lining of blood vessels) and can be broadly defined as an imbalance between vasodilating and vasoconstricting substances produced by (or acting on) the endothelium. "Ang II infusion caused endothelial dysfunction in the aorta, as determined by the effect of ACh to induce maximal relaxation of the aorta pre-constricted with PE (54% Cyp1b1+/+ vehicle-treated group)." (PMID 31948482, 2020). "This diminished ability of Ang II to increase BP in female Cyp1b1+/+ mice is associated with decreased cardiac and vascular smooth muscle remodeling, reduced endothelial dysfunction, and decreased vascular reactivity to PE and ET-1." (PMID 31948482, 2020). "The 6β-OHT treatment restored the effect of Ang II to cause endothelial dysfunction in both the intact Cyp1b1−/− and castrated Cyp1b1+/+ and Cyp1b1−/− mice (59%, 50%, 53%, respectively) as determined by the loss of relaxation of the aorta by ACh (88%)." (PMID 31948482, 2020). "However, concurrent administration of 6β-OHT restored the effects of Ang II to increase aortic reactivity to PE and ET-1 and cause endothelial dysfunction, hypertrophy, and fibrosis in castrated Cyp1b1+/+ mice." (PMID 31948482, 2020). "CYP1B1 is involved in regulating metabolic pathways, including steroid hormone, fatty acid, vitamin, and melatonin metabolism, which are linked to the development of metabolic diseases such as metabolic syndrome, insulin resistance, hepatic steatosis, inflammation, and endothelial dysfunction." (PMID 39872609, 2024). "Previously, we reported that Cyp1b1 gene disruption or chemical inhibition of CYP1B1 activity minimized the Ang II-induced increase in vascular reactivity to vasoconstrictor agents, increased vascular ROS production, and endothelial dysfunction." (PMID 31948482, 2020). "Ang II infusion also caused endothelial dysfunction as indicated by the attenuation of relaxation to ACh, but not to SNP in the aorta of Cyp1b1+/+ male mice." (PMID 31948482, 2020). "Ang II infusion caused endothelial dysfunction, as indicated by decreased relaxation of the aorta to acetylcholine in Cyp1b1+/+ but not Cyp1b1−/− or castrated Cyp1b1+/+ and Cyp1b1−/− mice." (PMID 31948482, 2020). "This is supported by a recent finding demonstrated that Ang-II caused oxidative stress, cardiovascular changes, endothelial dysfunction and enhanced vascular reactivity in Cyp1b1(−/−) but not in Cyp1b1(+/+) female mice." (PMID 29426916, 2018). "Moreover, the increased constrictor responses associated with endothelial dysfunction have been ascribed to the reduction in NO-mediated inhibition of the potent vasoconstrictor 20-HETE, with subsequent ROS elevation via CYP1B1-dependent NADPH oxidase activity." (PMID 36297480, 2022). "6β-OHT did not alter Ang II-induced endothelial dysfunction in Cyp1b1+/+ mice but restored it in Cyp1b1−/− or castrated Cyp1b1+/+ and Cyp1b1−/− mice." (PMID 31948482, 2020).
atherosclerosis (8 papers, 2013 to 2024). A disease characterized by the build-up of fatty material and calcium deposition in the arterial wall resulting in partial or complete occlusion of the arterial lumen. "Recent findings have shown that CYP1B1 contributes to the development of atherosclerosis, DL, and HTN in rats; demonstrates an association with DM; and has a suggested influence on adipogenesis." (PMID 33632238, 2021). "In animal model studies, CYP1B1 was found to play a crucial role in the development of hyperlipidemia, atherosclerosis, and generation of reactive oxygen species (ROS)." (PMID 34385920, 2021). "In vitro studies have suggested the contribution of CYP1B1-mediated formation of genotoxic metabolites and DNA adducts in the development of atherosclerosis by polyaromatic hydrocarbons." (PMID 33185690, 2020). "Notably, CYP1A1 and CYP1B1 have been shown to reduce atherosclerosis and vascular dysfunction, respectively." (PMID 37063962, 2023). "Likewise, CYP1B1-mediated formation of genotoxic metabolites and DNA adducts lead to atherosclerosis and cardiovascular disease, and may also contribute to CYP1B1-mediated carcinogenesis." (PMID 33185690, 2020). "In this network, smoking was directly connected to 2 genes, CYP1B1 and HOXA10, which both have relevance to atherosclerosis and smoking." (PMID 23372645, 2013).
breast tumor (8 papers, 2008 to 2022). "The results of these studies indicate that CYP1B1 expression augments multiple phenotypes associated with aggressive characteristics of TNBC, and that elevated expression in breast tumors is associated with poor prognosis." (PMID 36077068, 2022). "Further extending these data, the current results demonstrate that 3MC engages GPER toward the up-regulation of both CYP1B1 and the cell-cycle regulator cyclin D1 in breast tumor cells and major components of the cancer stroma as CAFs." (PMID 31370872, 2019). "In this regard, we have recently demonstrated the involvement of GPER in the estrogen regulation of CYP1B1 that, in turn, prompted growth effects in diverse breast tumor models." (PMID 31370872, 2019). "However, higher CYP1B1 mRNA and protein levels are observed in breast tumors as compared to normal tissues." (PMID 25257533, 2014). "The differential expression of cytochrome P450s such as CYP1B1 protein in breast tumour samples, as opposed to normal tissue, has been proposed as a target for cancer chemotherapy." (PMID 18454852, 2008). "Finally, as pCR is rarely achieved by NCT in ER+ breast tumors, we searched if BRCA1 (Pro871Leu), ERCC1 (Asn118Asn), CYP1B1 (Leu432Val) and SLCO1B3 (IVS12-5676) could stand for predictive markers of NCT for patients with this subtype of tumor." (PMID 26180747, 2015).
melanoma (8 papers, 2011 to 2024). A malignant, usually aggressive tumor composed of atypical, neoplastic melanocytes. "In melanoma, the correlation was particularly strong in tumors expressing high levels of IDO (IDOhigh) and non-existent in those expressing low levels of IDO (IDOlow), with similar observations when categorizing tumors by CYP1B1 expression." (PMID 32782249, 2020). "In a bivariate analysis combining the nevus results with a recent melanoma GWAS meta-analysis (12,874 cases, 23,203 controls), SNPs near GPRC5A, CYP1B1, PPARGC1B, HDAC4, FAM208B, DOCK8, and SYNE2 reached global significance, and other loci, including MIR146A and OBFC1, reached a suggestive level." (PMID 30429480, 2018).
Sepsis (8 papers, 2023 to 2026). Sepsis is defined as life-threatening organ dysfunction caused by a dysregulated host response to infection. "Lastly, we used another four datasets to validate the expression change and diagnostic performance of CYP1B1 in sepsis patients." (PMID 41212877, 2025). "CYP1B1 was high expression in Wnt5A-associated inflammatory, cardiovascular diseases, and sepsis." (PMID 39262873, 2024). "ROC curve analysis was performed to evaluate the diagnostic value of ABCC1, CYP1B1, and PPARG in sepsis patients." (PMID 41509654, 2026). "Using machine learning algorithms, we identified three key diagnostic genes for sepsis (ABCC1, CYP1B1, and PPARG) with high reliability and broad applicability." (PMID 41509654, 2026). "Our analysis showed a strong positive correlation between CYP1B1 and M0 macrophages, implicating its involvement in driving the cytokine storm characteristic of sepsis." (PMID 41509654, 2026). "Wilcoxon test demonstrated that CYP1B1 was obviously upregulated in sepsis samples, when compared with healthy samples." (PMID 41212877, 2025). "Among these genes, CYP1B1 appears to enhance disease progression and holds promise as a biomarker for sepsis diagnosis and progression." (PMID 41212877, 2025). "This emphasized the potential of targeting CYP1B1 and tryptophan metabolism pathways as therapeutic strategies in sepsis." (PMID 41212877, 2025). "In this study, we found that the expression of tryptophan metabolism-related CYP1B1 was significantly increased in blood samples of septic patients, indicating its potential as a hazardous gene in sepsis." (PMID 41212877, 2025). "We verified the expression level of CYP1B1 using four external datasets (GSE69063, GSE95233, and GSE131761) and found that CYP1B1 was significantly upregulated in sepsis group when compared with con group (P < 0.05)." (PMID 41212877, 2025). "CYP1B1 is involved in tryptophan metabolism and its upregulation can promote the progression and development of sepsis through activating monocytes." (PMID 41212877, 2025). "Overall, these outcomes indicated the strong predictive capability of CYP1B1 in exclusive diagnosis of patients with sepsis cases from healthy volunteers." (PMID 41212877, 2025). "Furthermore, single-cell sequencing analysis further indicated that CYP1B1 was primarily expressed in monocytes, and its’ expression level was significantly upregulated in monocytes activated by sepsis/LPS." (PMID 41212877, 2025). "The therapies targeting modulation of CYP1B1 activity or tryptophan metabolism could influence the sepsis deterioration and improve patient prognosis." (PMID 41212877, 2025). "However, the cellular and molecular mechanisms by which CYP1B1 impacts the development and progress of sepsis need further elucidation." (PMID 41212877, 2025). "Furthermore, receiver operating characteristic (ROC) curve analysis was conducted to assess the effectiveness of CYP1B1 for predicting sepsis." (PMID 41212877, 2025). "One tryptophan metabolism-related DEG for sepsis were obtained, namely CYP1B1." (PMID 41212877, 2025). "Importantly, analysis of single-cell sequencing results further showed that CYP1B1 was expressed in the monocytes, indicating CYP1B1 probably involves in the development of sepsis by regulating the activity and function of monocytes." (PMID 41212877, 2025). "In addition, CYP1B1 was also found to exhibit strong predictive capability in exclusive diagnosis of patients with sepsis cases from healthy volunteers." (PMID 41212877, 2025). "The results of RT-PCR indicated that MAPK14 and CYP1B1 were highly expressed in sepsis samples." (PMID 37398680, 2023). "Importantly, we identified six critical genes, including CS, CYP1B1, FLVCR1, IFIT2, MAPK14, and PID1, which showed favorable diagnostic value in screening sepsis samples from normal samples." (PMID 37398680, 2023).
Sepsis (continued). "Finally, we collected 15 sepsis samples and 15 normal samples and performed RT-PCR to examine the expression of CS, CYP1B1, FLVCR1, IFIT2, MAPK14, and PID1 in our cohort, which further confirmed our previous findings." (PMID 37398680, 2023). "In our results, two cytochromes were identified as DEGs in sepsis P450, CYP1B1, and CYP4V2." (PMID 36820206, 2023). "Notably, CYP1B1 exhibited great discriminative ability for the diagnosis of sepsis." (PMID 41212877, 2025). "Besides, the cytochrome P450 gene CYP1B1 also showed diagnostic values for sepsis from the non-sepsis diseases." (PMID 36820206, 2023). "Among sepsis patients, ABCC1 was identified as a low-expression gene, while CYP1B1 and PPARG were identified as high-expression genes." (PMID 41509654, 2026). "Single-cell analysis further revealed that ABCC1, CYP1B1, and PPARG are highly expressed in monocytes, which are central to the immunopathology of sepsis, acting as key mediators of both inflammation and immune suppression." (PMID 41509654, 2026). "The results demonstrated that ABCC1 was significantly downregulated, while CYP1B1 and PPARG were significantly upregulated in the sepsis organoids." (PMID 41509654, 2026). "The Venn diagram shows that a total of eight overlapping genes were discovered between ACSL4 co-expression genes and sepsis, including GK, CLEC4E, ACSL1, TGFBR3, ADAM9, AZI2, BCAT1, and CYP1B1." (PMID 39262873, 2024). "The genes TPSO, CYP1B1, LCN2, CLIC2, and ELL2 were up-regulated and FTO was down-regulated in sepsis compared to the uncomplicated infections (p < 0.05)." (PMID 36820206, 2023). "Using bioinformatics techniques, we identified PID1, CS, CYP1B1, FLVCR1, IFIT2, and MAPK14 as six MRGs that are essential in the course of sepsis." (PMID 37398680, 2023). "Additionally, three key genes (ABCC1, CYP1B1, and PPARG) were identified based on Prevotella 9, fatty acids, and PANoptosis, contributing to sepsis progression via the regulation of neutrophils, oxidative stress, and macrophage polarization." (PMID 41509654, 2026). "Additionally, the predominant expression of ABCC1, CYP1B1, and PPARG in monocytes underscores the critical role of monocyte functional reprogramming in sepsis pathogenesis." (PMID 41509654, 2026). "During sepsis, the bone marrow releases a large amount of immature granulocyte (IGs) through emergency granulopoiesis, such as CEACAM8+Neu, S100A8/9hiNeu, IL1R2+Neu, PADI4+Neu, MPO+Neu and cycling MK167+CYP1B1+Neu." (PMID 40356926, 2025). "Further ROC analysis suggested the AUC of LCN2 and CYP1B1 in diagnosis between sepsis and uncomplicated infectious or noninfectious diseases were both >0.66." (PMID 36820206, 2023). "Additionally, when compared to sepsis shock, we found TPSO, GCLM, CYP1B1, LCN2, and LTF were up-regulated and the FTO and CYP4V2 were down-regulated in the sepsis (p < 0.05)." (PMID 36820206, 2023). "CYP1B1 was found to be up-regulated simultaneously in sepsis vs healthy controls, sepsis vs non-infection disease, and sepsis vs uncomplicated infections, while CYP4V2 was down-regulated simultaneously in sepsis vs healthy controls, sepsis shock vs sepsis, and severe sepsis vs mild sepsis." (PMID 36820206, 2023). "We found that the expression of MAPK14 and CYP1B1 was distinctly increased in sepsis samples compared with normal samples, while the expression of PID1, CS, FLVCR1, and IFIT2 was distinctly decreased in sepsis samples compared with normal samples." (PMID 37398680, 2023).
gastric cancer (7 papers, 2021 to 2025). A primary or metastatic malignant neoplasm involving the stomach. "Our study found that the common variant of the phase I CYP1B1, rs1800440, conferred approximately 40% increased risk of gastric cancer even after adjusting for age, sex, CagA status and wood stove use in analyses without a SNP-wood stove interaction term." (PMID 37783717, 2023). "Male sex (OR 2.0, 1.6–2.6), age (OR 1.04, 1.03–1.05), wood cookstove use (OR 2.3, 1.6–3.3), and CagA serostatus (OR 3.5, 2.4–5.1) and two SNPs in CYP1B1 (rs1800440 and rs1056836) were independently associated with gastric cancer in multivariate analysis." (PMID 37783717, 2023). "We verified through clinical specimens of gastric cancer liver metastasis that higher expression of CYP1B1 correlates with a stronger metastatic potential of gastric cancer cells." (PMID 40263929, 2025). "The results indicated that low expression of CYP1B1 inhibited the migration of gastric cancer cells." (PMID 40263929, 2025). "Clinical tissue samples of gastric cancer liver metastasis were selected, and the results of qRT‐PCR and WB showed that the expression of CYP1B1 increased sequentially in normal tissue, gastric cancer tissue, and liver metastatic tissue." (PMID 40263929, 2025). "For modeling the anoikis of gastric cancer cells, gastric cancer cells were cultured in ultra‐low attachment plates for 24 h, and the qRT‐PCR results showed that CYP1B1 expression was higher than in the non‐suspended group." (PMID 40263929, 2025). "The chemical carcinogenesis‐reactive oxygen species signaling pathway was activated in a CYP1B1 high‐expression group, whereas some cancer pathways such as gastric cancer and Cushing syndrome were triggered in the low‐expression group." (PMID 38376054, 2024). "The activation of AHR and CYP1A1 and CYP1B1 related pathways promotes the proliferation and migration of gastric cancer cells." (PMID 34784845, 2021). "Additionally, by constructing an anoikis model and conducting related experiments, we demonstrated that CYP1B1 can enhance the anoikis resistance of gastric cancer cells, promoting their migration and growth." (PMID 40263929, 2025). "Especially in gastric cancer cells, lncRNA UCA1 promotes the upregulation of CYP1B1 (cytochrome P450 family 1 subfamily B member 1) through sponging miR-513a-3p, resulting in cisplatin resistance and cancer cell proliferation." (PMID 36499136, 2022). "MiR-513a-3p had the same binding site to CYP1B1, low miR-513a-3p levels enhance CYP1B1 expression, conferring DDP-resistance by reducing DDP-induced apoptosis in gastric cancer cells." (PMID 35444536, 2022). "To analyze the impact of CYP1B1 on the malignant behavior of gastric cancer, we quantified its expression in normal gastric cells (GES‐1) and GC cell lines (MKN45, AGS, HGC27), with the highest expression of CYP1B1 observed in MKN45 cells." (PMID 40263929, 2025). "However, the role of CYP1B1 in gastric cancer anoikis has not been studied." (PMID 40263929, 2025).
head and neck cancer (7 papers, 2014 to 2023). A primary or metastatic malignant neoplasm affecting the head and neck. "This frequent CYP1B1 polymorphism is crucial for cancer cell proliferation, migration, resistance to chemotherapy and stemness properties, and strongly influences head-and-neck cancer patients’ survival." (PMID 32565541, 2020). "Simultaneously, the expression of the cytochrome P450 subtypes 1A1 and 1B1 (CYP1A1 and CYP1B1) genes increased in the head and neck cancer (HNC) cell line, elucidating the involvement of cytochrome P450 in OSCC." (PMID 35096060, 2022). "Harth et al33 analysed polymorphisms of genes in head and neck cancer and in a subgroup of non‐smokers, variants of the ERCC2 gene were predominant but when stratifying for smokers, CYP1B1 variant produced main effect." (PMID 30133114, 2018). "Attenuation of CYP1B1 expression has been found to decrease the proliferative activity, cell migration capability and invasiveness of endometrial and head and neck cancer cell lines." (PMID 26626260, 2015). "CYP1B1 was reported to drive cancer cell stemness and patient outcome in head-and-neck carcinoma." (PMID 35464409, 2022).